ERCC2 (ERCC excision repair 2, TFIIH core complex helicase subunit)
Diseases named in the same sentence as ERCC2 in open-access papers (continued):
Sharing a sentence is not in itself a finding about the gene and the disease.
ototoxicity (1 paper, 2018). damage to the ear, specifically the cochlea or auditory nerve as a result of some toxic stimulus, eg from a drug. "Furthermore, the patients with the C/C wild type genotype at rs1799793 in ERCC2 had significantly 4.1 times higher risk to develop ototoxicity (95% CI 1.43–11.52; P = 0.008)." (PMID 30112115, 2018).
papillary carcinoma (1 paper, 2022). A malignant epithelial neoplasm characterized by a papillary growth pattern.
Primary amenorrhea (1 paper, 2020). "Herein, a rare heterozygous variant (c.1606G>A;p.Val536Met) in ERCC2 was identified in POI-30, who was diagnosed with isolated primary amenorrhea." (PMID 33095795, 2020).
stomatitis (1 paper, 2020). Inflammation of the oral mucosa due to local or systemic factors. "In patients receiving adjuvant chemotherapy, the ERCC1-rs11615 genotype T/T was significantly associated with stomatitis (p = 0.03), and significantly more patients with the ERCC2-rs13181 C allele needed dose reduction compared to patients with the A/A genotype (p = 0.02)." (PMID 32397974, 2020).
triple-negative breast carcinoma (1 paper, 2014). An invasive breast carcinoma which is negative for expression of estrogen receptor (ER), progesterone receptor (PR), and human epidermal growth factor receptor 2 (HER2). "In the present work, a relationship was identified between ERCC2-Lys751Gln polymorphism and the incidence of triple-negative breast cancer." (PMID 24402573, 2014). "The aim of this study was to evaluate the role of the hOGG1-Ser326Cys (rs13181), XRCC1-Arg194Trp (rs1799782), and ERCC2-Lys751Gln (rs13181) gene polymorphisms with clinical parameters and the risk for development of triple-negative breast cancer." (PMID 24402573, 2014). "We suggest that the Lys751Gln polymorphism of the ERCC2 gene may be risk factors for triple-negative breast cancer development in Polish women." (PMID 24402573, 2014). "The obtained data suggest that the reported study may be the first observation of the polymorphisms in ERCC2, hOGG1, and XRCC1 genes, involved in the DNA repair pathway, to be associated with triple-negative breast carcinoma risk in the population of Polish women." (PMID 24402573, 2014).
tumors of the urinary tract (1 paper, 2021). "Our EA analysis coupled with a detailed mutational map enables the prediction that selection pressure is operative for at least some DNA repair genes, such as ERCC2, in patients with a medium mutational burden, particularly those affected by tumors of the urinary tract." (PMID 34966786, 2021).
Wilms tumor (1 paper, 2022). An embryonal neoplasm characterized by the presence of epithelial, mesenchymal, and blastema components. "The ERCC2 rs3810366 and rs238406 polymorphisms were shown to significantly enhance Wilms tumor susceptibility." (PMID 35955506, 2022).
cancer (113 papers, 2007 to 2026). A tumor composed of atypical neoplastic, often pleomorphic cells that invade other tissues. "The impact of ERCC2 polymorphisms, a helicase involved in nucleotide excision repair, has been extensively investigated in various cancers, including gynecological tumors." (PMID 41374450, 2025). "Stratification of OS analysis by cancer type revealed that both SNPs of ERCC2 were associated only with HNSCC patients in our cohort under a dominant genetic model." (PMID 40526606, 2025). "Some polymorphisms of the ERCC2 gene are associated with a high risk of developing various types of cancer, such as breast cancer, lung cancer, hepatocellular cancer, and leukemia." (PMID 39699591, 2025). "Previously, data on survival in relation to ERCC2 gene polymorphisms have varied across different populations and cancer types, limiting their application in clinical practice." (PMID 40526606, 2025). "Deficiency in ERCC1 and ERCC2 can lead to a higher accumulation of DNA damage, which increases the likelihood of mutations that can ultimately lead to cancer development." (PMID 39834980, 2024). "Further studies are needed to fully understand the connection between ERCC1 and ERCC2 deficiencies and cancer risk, as well as to explore potential therapeutic strategies for individuals with these deficiencies." (PMID 39834980, 2024). "The ERCC2 & AGE signature included one signature mediated by ERCC2 mutations and another signature correlated with the age of cancer diagnosis." (PMID 36495164, 2023). "ERCC2 was another gene related to DNA repair (nucleotide excision repair pathway), that was associated with cancer survival (5 studies)." (PMID 35444210, 2022). "Among them ERCC2, encoding the Xeroderma Pigmentosum Protein, is frequently altered in different types of cancer." (PMID 34330313, 2021). "Recent genomic profiling clarified that ERCC2 mutations were relatively enriched in 6.7% of urothelial BC compared with several other cancers." (PMID 32984035, 2020). "With regard to previous cancer history and cardiovascular disease, an association with ERCC2 was observed." (PMID 31924810, 2020). "Associations between XRCC1, XRCC3, and ERCC2 gene polymorphism and prognosis have been investigated in several cancers." (PMID 31281357, 2019). "Some studies have reported the association between ERCC2 mRNA expression and prognosis in patients with malignant tumors." (PMID 30417012, 2018). "In the relationship between gene polymorphisms and cancer risk, the ERCC2 Asp312Asn polymorphism is an important risk factor." (PMID 28489582, 2017). "In order to evaluate the effects of specific study characteristics on the association between the ERCC2 polymorphism and cancer risk, we performed subgroup analysis if there were 6 or more studies." (PMID 28489582, 2017). "In our meta-analysis, the association of the ERCC2 Asp312Asn polymorphism with the risk of cancer was evaluated in 38,848 cases and 48,928 controls." (PMID 28489582, 2017). "Overall, the results of our meta-analysis showed a significant association between the ERCC2 polymorphism and cancer risk." (PMID 28489582, 2017). "To date, many publications have shown an association between the ERCC2 Asp312Asn polymorphism and risk of cancer." (PMID 28489582, 2017). "In summary, our meta-analysis suggested that the ERCC2 Asp312Asn polymorphism is associated with increased cancer risk." (PMID 28489582, 2017). "Some previous meta-analyses assessed the effect of the ERCC2 Asp312Asn polymorphism on the risk of these cancers and reached conclusions consistent with those of our study." (PMID 28489582, 2017). "In order to resolve this conflict, we performed a meta-analysis that evaluates the relationship between the ERCC2 Asp312Asn polymorphism and risk of cancer." (PMID 28489582, 2017). "The overall analysis suggested a significant association between the ERCC2 Asp312Asn polymorphism and cancer risk." (PMID 28489582, 2017).
cancer (continued). "A significant association was observed between the ERCC2 Asp312Asn polymorphism and overall cancer risk in all genetic models." (PMID 28489582, 2017). "For control source subgroup, we found a significant association between the ERCC2 polymorphism and cancer risk when the source of the controls was hospital-based (HB)." (PMID 28489582, 2017). "As the most frequently assessed variant, the ERCC2 Lys751Gln polymorphism is thought to be associated with many cancers." (PMID 28223548, 2017). "In summary, our results suggested that ERCC2 Asp312Asn polymorphism is associated with increased cancer risk." (PMID 28489582, 2017). "To provide a comprehensive assessment of and to clarify associations between the ERCC2 Asp312Asn polymorphisms and the risk of cancer, we performed a meta-analysis of all the eligible case-control studies." (PMID 28489582, 2017). "There is contrasting evidence on the association between the ERCC2 Asp312Asn polymorphism and the risk of cancer." (PMID 28489582, 2017). "The Asn118Asn (rs11615) variant in the ERCC1 gene, and the Lys751Gln (rs13181) and Asp312Asn (rs1799793) variants in the ERCC2 gene have been associated with the development of varied types of cancer." (PMID 25789018, 2015). "The aim of the present study was to test for any association between the ERCC1 and ERCC2 gene variants and three different types of cancer in Mexican-mestizo patients." (PMID 25789018, 2015). "ERCC2 has a Lys/Gln polymorphism, the derived (major) allele of which confers enhanced DNA repair capacity and reduced cancer risk compared with the ancestral (minor) allele." (PMID 23157318, 2012). "The risk in the carriers of the ERCC2 751Gln variant was increased by a positive cancer history in first degree relatives (OR 4.97; 95 % CI 1.98–12.48)." (PMID 22544315, 2012). "Adjustment for first degree relatives cancer history increased OR for the Gln/Gln genotype of the p.Lys751Gln polymorphism of ERCC2 gene from OR 3.95; 95 % CI 1.88–8.31 to OR 4.97; 95 % CI 1.98–12.48." (PMID 22544315, 2012). "Polymorphisms in ERCC1 and ERCC2 could alter the ability to repair DNA, thereby affecting the response or survival of cancer patients." (PMID 36980706, 2023). "Among these genes, ERCC2 is of particular interest, as it plays an important role in the nucleotide excision repair pathway, and common polymorphisms in this gene have been associated with risk of various types of cancers." (PMID 35884425, 2022). "Mutational analysis of 5243 cancer genome sequences (4633 exomes and 610 whole genomes) of smoking-related cancers has revealed a signature (signature 5) that harbors inactivating mutations in ERCC2 which encodes a component of nucleotide excision repair." (PMID 35681556, 2022). "Potentially actionable mutations that we identified include an ERCC2 nonsynonymous mutation that is indexed in both the Catalogue of Somatic Mutations in Cancer (COSMIC) and OncoKB and correlates strongly with increased sensitivity to cisplatin-based chemotherapy." (PMID 34464379, 2021). "The present investigation showed that higher ERCC2 expression was associated with poor patient survival, and ERCC2 protein levels can be markedly higher in cancer vs. normal tissue, implying that drugs that target ERCC2 for downregulation are likely to have broader safety and therapeutic efficacy." (PMID 33809839, 2021). "A total of 18% (≈4 mutations) of virus-negative and 16% (≈2 mutations) of virus-positive frameshift InDels are within Hallmark Gene Sets, among those annotated as pathogenic and cancer-related in ClinVar are ERCC2 in UM-MCC9 (chr19.45855805.T > -), and BRCA2 in UM-MCC29 (chr13.32911298.AAAC > -)." (PMID 33562873, 2021). "Third, a single gene has only a moderate effect on cancer development; hence, the ERCC2 gene may influence susceptibility of cancer along with other genes." (PMID 28489582, 2017).
cancer (continued). "Because of the important role of ERCC2 it is believed that even mild modifications of its sequence or structure may be significant for DNA repair efficiency, cancer risk and clinical effects of cytotoxic treatment." (PMID 27527855, 2016). "Using ERCC2 DNA repair gene as an example, we show that proof of a possible role in cancer susceptibility requires a detailed dissection and characterization of the underlying mutations for genes with diverse cellular functions (in this case mainly DNA repair and basic cellular transcription)." (PMID 27504877, 2016). "Variant 751Gln allele of ERCC2 increased cancer risk (OR 3.61; 95% CI 2.92–4.45; p < 0.0001)." (PMID 26526682, 2015). "Because a proper functioning of the ERCC2 gene is important for the genomic stability, its alternations may be associated with higher cancer susceptibility." (PMID 24402573, 2014). "ERCC2 is indispensable for nucleotide excision repair pathway, and its functional polymorphisms may be associated with cancer risk." (PMID 25209371, 2014). "The data obtained suggest also that positive cancer history in first degree relatives in connection with Gln/Gln variant of the p.Lys751Gln polymorphism of the ERCC2 gene may be associated with EC." (PMID 22544315, 2012). "Because a proper functioning of the ERCC2 gene is important for the genomic stability, its alternations may be associated with a higher cancer susceptibility." (PMID 22544315, 2012). "Caucasian CRC cancer patients presented with ERCC2 AC as the most common polymorphism genotype." (PMID 18267032, 2008). "Therefore, ERCC2 is a plausible candidate gene for cancer susceptibility." (PMID 27504877, 2016). "Individuals with inherited ERCC2 defects display their disease phenotype in a recessive genetic model, because only the homozygotes are prone to accumulate genetic damage and may have a marked predisposition to cancer." (PMID 25209371, 2014). "Therefore, potentially functional ERCC1 and ERCC2 SNPs may affect cellular DNA repair capacity and thus may be associated with various survival rates observed in cancer patients." (PMID 24023723, 2013). "DNA damage plays an important role in cancer development, and the proteins encoded by XRCC1 and ERCC2 are important components of the DNA repair system." (PMID 39699591, 2025). "Genetic polymorphisms in ERCC2/XPD, a crucial component in NER, are believed to be linked with cancer risk development." (PMID 35683027, 2022). "Several cancers overexpress ERCC2, resulting in poor response to chemotherapy or radiation therapy, as demonstrated in late-stage CRC." (PMID 33809839, 2021). "We conclude that further studies are warranted into the clinical relevance of ERCC2, a key cellular DNA repair protein, as a potential biomarker and therapeutic target for cancer interception and epigenetic combination therapy." (PMID 33809839, 2021). "Higher ERCC2 expression was detected in cancer versus normal, as observed before, but there were no obvious differences in ERCC2 expression between SW620 and SW480." (PMID 33809839, 2021). "Another two probands carried likely pathogenic variants of other genes known to be associated with a genetic predisposition toward cancer (EXT2 = 1, ERCC2 = 1)." (PMID 34567566, 2021). "The human homologue of the yeast gene RAD3 named XPD/ERCC2 which encodes for a DNA helicase involved in NER, has been demonstrated to be associated with several cancers." (PMID 32656256, 2020). "With regard to previous cancer history, the ERCC2 gene, also involved in nucleotide excision repair, showed an association under allelic model (rs13181, rs713041) and dominant model (rs1052133)." (PMID 31924810, 2020). "So far, the altered DNA repair activity of the ERCC1 and ERCC2/XPD variants has been considered central for its association with tumor risk and cancer patient outcome." (PMID 30847299, 2019).
cancer (continued). "BRCA2, BLM, ERCC2, RECQL, REV3L and RIF1 were among the most promising candidates, with some of them previously associated with predisposition syndromes to other cancers." (PMID 30871259, 2019). "In the CR group, miR-770-5p was strongly expressed in the cancer epithelium, but ERCC2 expression was weak or undetectable in the same tumor tissues from the same patient." (PMID 27449101, 2016). "In the present study, we found that the ERCC2/XPD rs238406 TT genotype was associated with a reduced DFS and OS in ESCC patients, but few studies have reported its role in prognosis of cancer patients." (PMID 27246611, 2016). "Thirty proteins, excluding RORA, XPC and ERCC2, are known to play important roles in the expression of malignant phenotypes involved in cancer initiation and/or progression, such as increased invasion, aberrant metabolism and enhanced survival." (PMID 26703734, 2015). "Single nucleotide polymorphism Lys751Gln (rs13181) is one of the most widely studied genetic markers in ERCC2 and its role in various cancers' development is evident." (PMID 26526682, 2015). "Allele and genotype frequencies of Asn118Asn (ERCC1) and rs13181 (ERCC2) were distributed according to the HWE model in each group in all types of cancer (P>0.05)." (PMID 25789018, 2015). "ERCC2 rs13181 and rs1799793 SNPs have also previously been investigated for their roles in cancer patient survival." (PMID 24023723, 2013). "The XPD gene, also known as excision repair cross-complementing rodent repair deficiency Group 2 (ERCC2), is important in environmentally induced cancer." (PMID 23028604, 2012). "Two studies using whole-exome-sequencing and DNA sequencing targeting 287 cancer-related genes respectively, found that alterations in DNA repair genes may correlate with response to chemotherapy: ERCC2, ATM, RB1, and FANCC." (PMID 36322407, 2022). "From variant analysis of 46 cancer susceptibility genes, we identified 7 pathogenic and likely pathogenic germline variants in 7 genes in 7 (8%) of the 87 patients, namely, MUTYH, RET, TSC2, BRCA1, BRCA2, ERCC2 and HRAS." (PMID 29684080, 2018). "This indicates that not all functionally relevant ERCC2 mutations increase cancer susceptibility in their carriers." (PMID 27504877, 2016). "XPD (ERCC2) gene, located at chromosome 19q13.3, comprises 23 exons and its polymorphisms are thought to engender structural alterations of NER pathway and influence cancer susceptibility." (PMID 23028453, 2012). "For the associations of ERCC2 polymorphisms with cancers, the negative findings may result from the low statistical power of available studies now." (PMID 24330540, 2013). "Various human XPD/ERCC2 mutations have been introduced into the corresponding murine gene and the disease phenotypes recapitulate well the human syndromes, although the relative severity of the cancer and neurological defects in specific mouse mutants has been somewhat unpredictable." (PMID 20840796, 2010). "At the genetic level, tumor mutation burden and alterations in DNA damage response and repair genes including ATM, ERCC2, BRAC-2, FANCA, MSH6, and POLE can to some extent predict the response of ICIs in specific cancer types." (PMID 33791296, 2021). "Linkage disequilibrium-mapping studies in Caucasians have indicated anassociation of Chr19q13.3 sub-region spanning ERCC2, PPP1R13L, CD3EAP and ERCC1 with several cancers." (PMID 27183913, 2016). "Changes in ERCC1, ERCC2, XRCC1, and XRCC3 may potentially influence cancer development by disturbing the DNA repair mechanism." (PMID 39834980, 2024). "There was a positive correlation between the expression of ERCC2 and most carcinomas, with only a mild negative correlation observed with OV." (PMID 39192988, 2024).
cancer (continued). "Emerging evidence associates the expression levels of genes involved in the NER process and some types of cancer, while data on STS are limited, so we evaluated the gene expression of three key genes (ERCC1, ERCC2 and ERCC5) in the NER pathway in 24 tissue samples from the 32 patients in our cohort." (PMID 35955506, 2022). "Moreover, the exact mechanism for the associations between different cancer sites and the ERCC2 Asp312Asn polymorphism is not clear; the mechanism of carcinogenesis may differ between different cancer sites and the ERCC2 genetic variants may exert varying effects in different cancers." (PMID 28489582, 2017). "Regulation of the nucleotide excision repair genes XPC and ERCC2 contributes to cancer prevention rather than progression, because the function of these genes is to maintain genomic integrity." (PMID 26703734, 2015). "Although there is little evidence of a link between cancer and the specific RAD23B, ERCC2, and GSTM1 variants identified here, previous studies have observed associations between one or more types of cancer and other variants on these three genes." (PMID 23637977, 2013). "However, in the literature ERCC2 and ERCC3 have no dominant link with cancer, whereas polymorphisms in ERCC4 have been linked to cancer predisposition." (PMID 38872153, 2024).